EGFR (epidermal growth factor receptor)
Diseases named in the same sentence as EGFR in open-access papers (continued):
Sharing a sentence is not in itself a finding about the gene and the disease.
cancer (continued). "Here, we found that NEU3 potentiates EGFR-mediated tumorigenesis through the stimulation of EGFR phosphorylation and Src activity, and these findings should provide a new tool for the development of cancer therapy by the suppression of NEU3 that activates EGFR-signaling." (PMID 25803810, 2015). "Furthermore, we developed isogenic pairs of CNX-2006-sensitive and -resistant cancer cells to address the mechanisms of resistance that may emerge upon constant and selective inhibition of the EGFR-T790M oncogene." (PMID 26015408, 2015). "Moreover, specific EGFR inhibition has been one of the key targets for cancer therapy." (PMID 25679210, 2015). "Consequently, EGFR is targeted in cancers using reversible, irreversible or antibody inhibitors." (PMID 25948104, 2015). "In addition targeting EGFR could be beneficial for cancer therapy by repressing cell growth, as well as inducing the apoptosis of cancer cells." (PMID 25997612, 2015). "Thus, targeted therapeutics developed against Eph receptors could potentially be a viable and effective treatment option against EGFR-positive cancers as well." (PMID 25879388, 2015). "It was shown that aberrant overactivation of epidermal growth factor receptor or insulin-like growth factor receptor signals trigger phosphatidylinositol 3-kinase (PI3K)/Akt protein kinases leading to a sequential phosphorylation of PRAS40 that in turn binds to 14-3-3 protein in cancer cells." (PMID 26337468, 2015). "Furthermore, we show that the oncogenic activity of the resulting C-terminal deletion mutants are efficiently inhibited by EGFR-targeted drugs including erlotinib, afatinib, dacomitinib as well as cetuximab, expanding the therapeutic rationale of cancer genome-based EGFR targeted approaches." (PMID 25826094, 2015). "Indeed, previous studies have suggested that human LL-37 is involved in carcinogenesis via multiple reporters, such as FPR2 (FPRL1), epidermal growth factor receptor, and ERBb2, although LL-37 and its fragments and analogs also show anticancer effects in various cancer cell lines." (PMID 26175965, 2015). "EGFR T790M mutation and mesenchymal-epithelial transition (MET) amplification have been demonstrated to be genetic causes of acquired resistance to TKI7, 8, However, genetic cause of intrinsic resistance to TKI in kinase-driven cancer patients remains unknown." (PMID 26076815, 2015). "Also, we speculate that combining antibodies and kinase inhibitors may bring synergistic effect in these patients, as dual EGFR inhibition has proven successful in several types of cancer." (PMID 25826094, 2015). "Finally, KRAS-G13D induced EGFR expression, senescence, and a distinct pattern of transcriptional changes that may help explain the improved response of patients with G13D-positive cancers to anti-EGFR therapies." (PMID 25705018, 2015). "Hence, the aim of this study was to determine whether simultaneous targeting of inflammatory pathways (5-LOX-COX) and EGFR at early stages would lead to blockade of progression of PanIN lesions to carcinoma." (PMID 26429877, 2015). "Thus, we wondered whether ARNO was over expressed in patients' cancer tissues and the over expression was correlated with EGFR and IGF-IR signaling." (PMID 24618737, 2014). "The resulting effects of activation of EGFR, Erk and NF-κB pathways include regulation of cell adhesion, cell cycle progression, cell migration, cell survival, differentiation, metabolism, proliferation and apoptosis, which are all dysregulated in many cancer types." (PMID 24495306, 2014). "Molecules that are responsible for the development of both cancer growth and metastasis are either abnormaly secreted from intracellular secretion vesicles like neuropeptides or released by shedding from the plasma membrane like Epidermal Growth Factor Receptor (EGFR) ligands." (PMID 25221642, 2014).
cancer (continued). "The phenomenon of molecular collaboration of EGFR with other partners on cell membrane represents an important feature of cancer progression and may in part explain why targeted therapy designed to circumvent EGFR signaling has yielded only modest clinical success in cancer patients." (PMID 24971315, 2014). "However, the linkage between oncogenic mutated EGFR and cancer cell metabolism has not yet been clearly elucidated." (PMID 24928511, 2014). "Here, the authors show that EGF receptor (EGFR) signalling is negatively regulated by glucocorticoids, and that EGFR inhibitor has stronger antitumour effects when administered during the resting phase, when glucocorticoids are low, offering potential optimization of cancer therapy regimens." (PMID 25278152, 2014). "However, accumulating evidence suggests that dysregulation of specific miRNAs may be involved in the acquisition of cancer cell resistance to EGFR-targeted agents." (PMID 25250326, 2014). "In anti-cancer research, retinoic acid has been investigated and found to inhibit the markers of cell proliferation, such as cyclin D1 and human telomerase reverse transcriptase (hTERT), and growth factor, such as epidermal growth factor receptor (EGFR) and vascular endothelial growth factor (VEGF)." (PMID 25520935, 2014). "In addition to its roles of modulating matrix assembly, fibrogenesis and cell proliferation, decorin displays anti-cancer activities through affecting signaling pathways of epidermal growth factor receptor (EGFR), transforming growth factor-beta (TGF-beta), and p21." (PMID 24625664, 2014). "As KRAS and BRAF mutations are associated with poor response to anti-EGFR therapy in some cancers, it has been suggested that screening for KRAS and BRAF mutations in RCC may be a promising strategy to identify patients who might respond to EGFR-targeted therapy." (PMID 28326248, 2014). "Thus, EGFR signaling is also critical for the development of many types of cancer." (PMID 24658383, 2014). "For this patient, the existence of 2 cancers might explain the presence of EGFR mutated and non-mutated samples." (PMID 24885034, 2014). "The possibility that in KRAS and BRAF mutant cancer cells differential signalling mechanisms that involve MEK, supported the mutual exclusivity of these two mutations, lead to the target-specific cancer therapeutics in the form of monoclonal antibodies against EGFR and VEGF receptors." (PMID 25361007, 2014). "Thus, it is important to control EGFR function in order to treat the cancer patients." (PMID 24992720, 2014). "Furthermore, since we have found that in several cancer cells GPCR-conveyed mitogenic signals may be mediated by pathways involving PKC or EGFR, or both in interaction, we also investigated the roles of these mechanisms." (PMID 24928086, 2014). "Interestingly, NSK-01105 exhibited dual inhibition of VEGFR2 and EGFR in both postate cancer cells." (PMID 25551444, 2014). "Furthermore, our results suggested that EGFR degradation was attributed to Erk inactivation-induced PDK4 up-regulation to decrease ATP and activate AMPK, providing the clue that AMPK activation might enhance anti-cancer of dasatinib through targeting EGFR." (PMID 24457597, 2014). "ANO1 has been shown to interact with cytoskeletal proteins and to promote epidermal growth factor receptor/calcium/calmodulin-dependent protein kinase signaling in cancer cells, yet a detailed understanding of the involvement of ANO1 in these pathways remains unclear." (PMID 24599954, 2014). "Given that exosomes express different forms of EGFR, the molecular target of Cetuximab, extracellular binding between Cetuximab and exosomal EGFR could reduce antibody binding to CRC cancer cells, partially neutralizing the effects of antibody-based therapeutics." (PMID 25594007, 2014).
cancer (continued). "While the human AGEF-1 proteins, BIG1 and BIG2, have not been previously implicated in EGFR signaling and cancer, mutations in BIG2 are causal of periventricular heterotopia, a condition whereby neurons fail to migrate to the cerebral cortex during brain development." (PMID 25329472, 2014). "The alternative to EGFR inhibitors currently used in cancer therapy, particularly with intended use in combination with other therapeutic modalities, may be non-toxic products of natural origin, such as general tyrosine kinase inhibitor, genistein or its derivatives." (PMID 25401399, 2014). "Therefore, the down-regulation of EGFR could exert anti-cancer effects on cancer cells with EGFR dependency as well as enhancing the efficacy of EGFR-TKIs in the setting of a decreased level of EGFR expression." (PMID 25486409, 2014). "Results suggest that nanoparticles derived from PC dispersion prepared in buffer pH 7.0 may induce physicochemical changes in the plasma membrane of cancer cells which may affect EGFR cellular localization and/or activity, increasing activation of the MEK-ERK1/2 pathway and inducing proliferation." (PMID 24772432, 2014). "Thus, the ability of berberine stimulated Cbl-dependent EGFR down-regulation may underscore its importance to suppressing diseases such as cancer." (PMID 23457600, 2013). "Furthermore, it is reported that when EGFR is overexpressed, it activates the signaling transduction system, and therefore cancer cells grow more aggressively, and with the invasiveness increasing, the transition occur more easily, affecting negative effects to the survival rate." (PMID 23706036, 2013). "Consequently, EGFR is the first growth factor receptor taken as cancer therapy target." (PMID 23613900, 2013). "Thus, cancer cells may become more dependent on the VEGF pathway when they acquire resistance to the EGFR inhibitor." (PMID 23420587, 2013). "Likewise, using the Reactome annotated pathways our method identified well known cancer-related pathways that regulate cell growth, death and proliferation including the EGFR signaling pathway, NF-kb activation, and Ras signaling pathway as commonly disrupted across many types of cancers." (PMID 23822816, 2013). "Such cancers may become sensitive to a second round of treatment with EGFR inhibitors." (PMID 23520442, 2013). "In addition, EGFt competed with EGFR native ligands, inhibiting the proliferation of cancer cells." (PMID 23935985, 2013). "Therefore, N-cadherin may serve as a promising new target for the treatment of cancers with acquired resistance to EGFR TKIs." (PMID 23520479, 2013). "Thus, targeting EGFR has been a fairly recent topic of research for cancer therapeutics, with a resultant series of potential molecular inhibitors that may be pursued in clinical oncology." (PMID 23407898, 2013). "The selection for EGFR amplification in our animal model, the coincidence of wtEGFR expression and invasion as an early process in tumorigenesis, and the stem-like properties of these cells described previously suggest a functional role for wtEGFR in cancer development." (PMID 23429996, 2013). "Further, we found that EGFR blocking could increase IL-6 in the cancer cells." (PMID 23592411, 2013). "Thus, HGF-induced inhibition of EGFR TKIs is shown to be a common occurrence in human cancers." (PMID 23407898, 2013). "Nimotuzumab’s low toxicity profile has made possible the intent of using an anti-EGFR agent in continuous, long-term treatment (lasting several months, and a few years in several cases), which has so far been administered to a few hundred advanced cancer patients." (PMID 23637683, 2013). "It is not clear whether the discrepancy is due to cell type specificity, but our results suggest that EGFR activity, rather than the absolute expression level of Mig6, underlies the response of cancer cells to anti-EGFR agents." (PMID 23935914, 2013).
cancer (continued). "Indeed, merely when already transformed cells with e.g. aberrant EGFR, HER/neu, or RAS mutations underwent EMT process, EMT could promote greatly tumorigenicity and generation of cancer stem cells." (PMID 23799116, 2013). "Finally, by targeting several components of the EGFR axis, miR-27a* may enhance the effect of existing treatment options and possibly provide therapeutic benefits to patients with EGFR-inhibitor resistant cancers." (PMID 23963114, 2013). "Thus, the expression of ERBB2, ERBB3 and ERBB4 in EGFR driven cancer may be important to predict the outcome of TKI treatment." (PMID 23758840, 2013). "In some patients, rare MET-amplified cells may be found in tissue samples before treatment, suggesting that EGFR-targeted therapies may act as a selective pressure to expand a preexisting subclonal population of cancer cells with MET amplification in a Darwinian fashion." (PMID 24005867, 2013). "Importantly, findings in VHL-/- cancer cells demonstrated that the shRNA-mediated inhibition of EGFR was sufficient to abolish HIF-2α-induced spheroid formation in a three-dimensional tumorigenic assay, which suggests that EGFR is required for HIF-2α-mediated tumorigenesis." (PMID 24376819, 2013). "Furthermore, cancer patients with over-expression of EGFR usually have poor prognosis." (PMID 23613900, 2013). "Therefore, EGFR is one of key targets of the therapeutic strategy designed to treat cancers." (PMID 23457600, 2013). "Thus EGFR is a target for therapeutic intervention in different cancer treatments." (PMID 24349439, 2013). "A better understanding of the effects of abnormalities in the EGFR system on cells will contribute to the understanding of the role of these abnormalities in cancer development, which, in turn, can lead ultimately to more effective cancer diagnosis, treatment, and prognosis." (PMID 25586035, 2012). "Therefore, identifying molecules that interact with the cytoplasmic domain of EGFR will contribute, not only to the elucidation of the regulatory mechanism of EGFR in cancer progression, but also to the development of new treatments for the uncontrolled growth of human cancers." (PMID 22476347, 2012). "Further, with respect to SCCHN, reports suggest that upwards of 90% of primary tumors also overexpress EGFR, a protein not typically observed on blood cells, which might also aid as a diagnostic marker for this cancer type." (PMID 22844540, 2012). "Again, such adapter proteins could mediate EGFR-specific entry of MHV into human cancer cells." (PMID 22312365, 2012). "The present study focuses on the development and the in vitro evaluation of a radiolabeled MNT possessing epidermal growth factor (EGF) as the ligand module, which ultimately might be suitable for targeting the many types of cancers overexpressing EGF receptors (EGFR)." (PMID 23107475, 2012). "Therefore, therapies suppressing MUC1 cleavage, including antagonists of EGFR and Src, might be beneficial in controlling a wide variety of malignant tumors." (PMID 22586492, 2012). "Furthermore, this strategy for gene-protein detection assays could be applied to other cancer biomarkers, such as EGFR and met proto-oncogene." (PMID 22647525, 2012). "The mutual expression of highly tumorgenic and metastatic-related genes, such as CD44, integrin α2β1, CD146, EGFR, and Flt-4, by epithelial- and mesenchymal-like cells indicates that cancer-stromal interactions of both types of cells may occur through common signaling pathways." (PMID 22330345, 2012). "Thus, this variation may lead to the different modifications of cancer genes, including EGFR, in tumorigenic pathways among different histological subtypes, gender and ethnicity." (PMID 23226726, 2012). "Moreover, EGFR is considered essential in cancer cell migration and the intravasation process." (PMID 22554015, 2012). "Moreover, most of the cancers acquire drug resistance due to the activation of EGFR pathway." (PMID 22952709, 2012).
cancer (continued). "Interestingly, ERβ1 positivity has recently been associated with better survival in triple-negative cancers that were treated with tamoxifen and inversely correlated with the expression of EGFR, an important marker in the immunohistochemical identification of basal-like cancers." (PMID 23158001, 2012). "Because Arf6 has been identified to play an important role in cancer cell migration and the PH domain of GEP100 links EGFR signaling to Arf6 activation, it is worthwhile to explore whether the PH domain of GEP100 is involved in EGF-induced Arf6 signaling pathway and cancer cell migration ability." (PMID 22701712, 2012). "EGFR-specific siRNAs may be good candidates for cancer therapy because of their specificity, efficiency, and endurance in gene-specific silencing and ability to suppress EGFR expression independent of the mutation status of the gene." (PMID 22436374, 2012). "However, in cancer cells, EGFR is involved in various pro-survival and anti-apoptotic pathways." (PMID 22952709, 2012). "However, under various circumstances RTK may be activated by cytoplasmic proteins, such as cytohesin, which activates EGFR while inhibition of cytohesin signalling downregulates proliferation of EGFR-dependent cancer cells." (PMID 22848811, 2012). "Herein, we report results of a case-case comparison, showing that cancers that are ER negative (as compared to ER positive) or EGFR positive (as compared to EGFR negative) are associated with a greater number of acini per TDLU and larger TDLU diameters, consistent with reduced involution." (PMID 22513288, 2012). "Finally, analysis of our microarray data suggested that miR-7 sensitizes EGFR-inhibitor resistant HNC cells to erlotinib by coordinately regulating expression of multiple molecules associated with activity of Akt, a critical downstream effector of EGFR and an emerging therapeutic target in cancer." (PMID 23115635, 2012). "Thus, the requirement for MUC1 in vitro and in vivo could represent a general mechanism to drive the metastatic phenotype for carcinoma cells which are dependent upon EGF/EGFR/Src signaling." (PMID 22586492, 2012). "In addition to the mutational status of KRAS, the epidermal growth factor receptor (EGFR) ligands amphiregulin (AREG) and epiregulin (EREG) might function as bona fide biomarkers of cetuximab (Ctx) sensitivity for most EGFR-driven carcinomas." (PMID 22491422, 2012). "This coincidence of PTEN loss and EGFR/HER2 gene/expression gain most likely represents an accumulation of independent genetic disorders in poorly differentiated carcinomas during tumourigenesis rather than a functional relationship between EGFR, HER2 and PTEN." (PMID 22240798, 2012). "Therefore, the information on EGFR mutation statuses in cancer tissue was not obtained from all the studied patients." (PMID 21791074, 2011). "In conclusion, the inhibitory properties of CL4 demonstrate its potential usefulness as a lead compound for the design of a new class of anticancer drugs and may become a valuable addition to the repertoire of inhibitors that target cancers that overexpress EGFR." (PMID 21915281, 2011). "Due to the flexible design and simple conjugation chemistry, this nanocarrier system could be used as a platform for the development of other MDR cancer therapies; the use of this system for EGFR-targeted, combination paclitaxel/lonidamine therapy is an advance in personalized medicine." (PMID 21931642, 2011). "The three remaining mutations had not yet been described in CRC nor in other cancers according to the EGFR databases and these affected codons 707 (TTG to TCG transition, L707S), 710 (ACT to GCT transition, T710A) and 711 (GAA to GTT double transversion Q711V)." (PMID 22026926, 2011). "Therefore, the EGFR has become an attractive target for cancer treatment." (PMID 22095231, 2011). "Therefore, the ability to target cancer stem cells may represent an important property for an anti-EGFR antibody." (PMID 24212794, 2011).